TTC7B (tetratricopeptide repeat domain 7B)
Description:
Component of a complex required to localize phosphatidylinositol 4-kinase (PI4K) to the plasma membrane. The complex acts as a regulator of phosphatidylinositol 4-phosphate (PtdIns(4)P) synthesis. In the complex, plays a central role in bridging PI4KA to EFR3B and HYCC1, via direct interactions.
Synonyms: TTC7L1; c14_5685
Tractability: Small molecule: a structure with a bound ligand is known. Antibody: UniProt places it where antibodies can reach, with high confidence; its Gene Ontology location is reachable by antibodies, with high confidence. PROTAC: ubiquitination databases record sites on it; its protein half-life has been measured.
Gene: Protein-coding gene on chromosome 14 (90,524,564 to 90,816,500, reverse strand). Ensembl gene ENSG00000165914.
Subcellular location: Cytoplasm, cytosol; Cell membrane
Subcellular location (Human Protein Atlas): Plasma membrane
Gene Ontology:
Molecular function: protein binding
Biological process: phosphatidylinositol phosphate biosynthetic process; protein localization to plasma membrane
Cellular component: cytosol; plasma membrane
Genetic constraint (gnomAD): Loss-of-function variants: 25 observed, 86.65 expected, observed/expected ratio (o/e) 0.29, 90% interval 0.21 to 0.4. The upper end of that interval is the gene's LOEUF score, 0.4, which puts it in group 1 of 6, group 1 being the genes least tolerant of losing a copy. Missense variants: 805 observed, 1,004.2 expected, observed/expected ratio (o/e) 0.8, 90% interval 0.76 to 0.85. Synonymous variants: 382 observed, 405.64 expected, observed/expected ratio (o/e) 0.94, 90% interval 0.87 to 1.02.
Homologues: Orthologues: macaque TTC7B (99% identical), dog TTC7B (98% identical), rat Ttc7b (97% identical), pig TTC7B (97% identical), mouse Ttc7b (97% identical), chimpanzee TTC7B (96% identical), guinea pig TTC7B (95% identical), tropical clawed frog ttc7b (89% identical), zebrafish ttc7b (83% identical), Caenorhabditis elegans ttc-7 (30% identical). Paralogues in human: TTC7A (51% identical), CFAP70 (14% identical), TTC6 (14% identical), TTC34 (12% identical), IFT88 (12% identical), TMTC1 (12% identical), TMTC2 (12% identical), OGT (12% identical), TMTC4 (12% identical), TMTC3 (11% identical), TTC16 (10% identical), TTC13 (9% identical), and 2 more.
Diseases named in the same sentence as TTC7B in open-access papers:
TTC7B is named in the same sentence as 25 diseases in open-access papers, as found by Europe PMC text mining. Sharing a sentence is not in itself a finding about the gene and the disease. The quoted sentences say what the papers report.
colon cancer (2 papers, 2025 to 2026). "We initially confirmed the correlation of the expression of these genes in colon cancer tissues from patients (n=105) and reported that TTC7B downregulation was significantly associated with poor prognosis." (PMID 39897037, 2025). "Although FTO-KO (or FTO-OE) inhibited (or enhanced) colon cancer cell proliferation, unexpectedly, we found that TTC7B-OE, which upregulates FTO expression, inhibited cell proliferation in an FTO-dependent manner." (PMID 39897037, 2025). "In the present study, we reported for the first time that TTC7B is another upstream regulator of TRm6A and colon cancer cell proliferation." (PMID 39897037, 2025). "Next, we evaluated the role of the FTO gene on the TTC7B-mediated inhibition of colon cancer cell proliferation using FTO-KO cell models." (PMID 39897037, 2025). "According to the qRT‒PCR analysis, baseline TTC7B mRNA was almost detectable in most of the 15 tested human cancer cell lines, and a medium expression level of TTC7B was detected in the colon cancer cell lines HCT116, LoVo, and SW480." (PMID 39897037, 2025). "Thus, we downregulated TTC7B expression (siTTC7B) in these colon cancer cells via two siRNAs targeting TTC7B mRNA (siTTC7B#1 and siTTC7B#2)." (PMID 39897037, 2025). "We further studied the effect of TTC7B on the proliferation of colon cancer cells and found that TTC7B-OE significantly inhibited the proliferation of HCT116, LoVo, and SW480 cells, whereas TTC7B-KO significantly increased the proliferation and colony formation of HCT116 and SW480 cells." (PMID 39897037, 2025). "Both FTO-KO and TTC7B-OE significantly inhibited the growth of LoVo cells in nude mice, and the loss of FTO abolished the effect of TTC7B-OE, suggesting a dominant effect of TTC7B over FTO on colon cancer cell proliferation." (PMID 39897037, 2025).
colorectal cancer (2 papers, 2025 to 2026). A primary or metastatic malignant neoplasm that affects the colon or rectum. "Our m6A-antibody-immunoprecipitated RNA sequencing (meRIP-seq) data further revealed that TTC7B-KO downregulated the mRNA m6A levels of genes related to endocytosis, infection, and colorectal cancer, according to the results of the mRNA pathway analysis." (PMID 39897037, 2025).
colon adenocarcinoma (1 paper, 2025). "Because TTC7B, FTO, and PI4KA expression is frequently downregulated in many cancers in the TCGA project, including colon adenocarcinoma (COAD), we performed a validation experiment using COAD and paired surgical margin (SM) samples from 105 patients." (PMID 39897037, 2025).
glioma (1 paper, 2023). A benign or malignant brain and spinal cord tumor that arises from glial cells (astrocytes, oligodendrocytes, ependymal cells). "Tetratricopeptide repeat domain 7B (TTC7B), a member of the tetratricopeptide repeat (TPR) gene family, is a protein‐coding gene linked to several diseases, including ischemic stroke and glioma." (PMID 37990988, 2023). "TTC7B, a protein‐coding gene involved in the phosphatidylinositol phosphate biosynthetic process and protein localization to the plasma membrane, has recently been recognized as a potential prognostic biomarker for glioma." (PMID 37990988, 2023).
head and neck squamous cell carcinoma (1 paper, 2023). A squamous cell carcinoma that arises from any of the following anatomic sites: lip and oral cavity, nasal cavity, paranasal sinuses, pharynx, larynx, and salivary glands. "However, in head and neck squamous cell carcinoma, kidney chromophobe, and pheochromocytoma & paraganglioma, the expression of TTC7B was higher than that in normal tissues." (PMID 37990988, 2023).
leukemia (1 paper, 2024). A malignant (clonal) hematologic disorder, involving hematopoietic stem cells and characterized by the presence of primitive or atypical myeloid or lymphoid cells in the bone marrow and the blood. "We first analysed the DA1-3b leukemia model and among the 70 commonly mutated genes in dormant leukemia DA1-3b/D365 and parental DA1-3b cells, ten genes (Ttc7b, Dnmt3b, Ap1b1, Ne1, Nedd4, Acy1, Cyp11a1, Htr2c, Magee1 and Gdi1) were amplified in dormant and parental cells." (PMID 39223638, 2024).
Obesity (1 paper, 2011). Accumulation of substantial excess body fat. "A number of novel obesity candidate genes were also identified (Thbs1, Ppp1r3d, Tmepai, Trp53inp2, Ttc7b, Tuba1a, Fgf13, Fmr) that have inferred roles in fat cell function." (PMID 21915269, 2011).
prostate carcinoma (1 paper, 2023). A carcinoma that arises from epithelial cells of the prostate gland. "Previous studies show TTC7B interact with PI4KIIIα in cytosol, we also detected the presence of this complex in prostate cancer cells." (PMID 37996444, 2023). "To determine the endogenous interaction of CXCR4 with PI4KIIIα adaptor protein TTC7B, we immunoprecipitated prostate cancer cells with CXCR4 and immunoblotted with TTC7B, PI4KIIIα and CXCR4." (PMID 37996444, 2023). "Similar to PI4KIIIα knockdown, TTC7B knockdown also significantly inhibited cellular invasion of prostate cancer cells suggesting that TTC7B adaptor mediated recruitment of PI4KIIIα to CXCR4 is critical for chemokine induced PC cell invasion." (PMID 37996444, 2023). "The data support this concept that in prostate cancer cells, endogenous interaction is present between CXCR4 and PI4KIIIα adaptor protein TTC7B." (PMID 37996444, 2023).
cancer (4 papers, 2023 to 2025). A tumor composed of atypical neoplastic, often pleomorphic cells that invade other tissues. "We found that the mRNA level of TTC7A is inversely and significantly associated with that of TTC7B in human cancer cell lines according to CCLE datasets (n=1037; r=-0.41)." (PMID 39897037, 2025). "These significant findings suggest that TTC7B's role in promoting cancer in HNSCC may be linked to its involvement in the regulation of ferroptosis." (PMID 37990988, 2023). "Through the analysis of TIMER2.0 online database, we found TTC7B was low expressed in 12 types of cancer and overexpressed in 3 tumors." (PMID 37990988, 2023). "In TTC7B siRNA transfected cells, both basal as well as chemokine-induced chemoinvasion is inhibited, suggesting that TTC7B regulates chemokine receptor-induced cancer cell invasion." (PMID 37996444, 2023). "As ferroptosis modulation presents a potential avenue for cancer treatment, understanding the mechanisms by which TTC7B influences this process could open up new possibilities for therapeutic interventions in HNSCC." (PMID 37990988, 2023). "Therefore, we speculate that overexpression of TTC7B might promote cancer progression by increasing macrophages levels in HNSCC." (PMID 37990988, 2023). "The TTC7B protein mainly localizes to the cytoplasm and plasma membrane and physically interacts with PI4KA, which activates several key signaling pathways, including the PI3K/AKT and MEK/ERK pathways, which promote cancer cell proliferation 26-28." (PMID 39897037, 2025). "While TTC7B has not been previously reported in HNSCC patients to date, there have been numerous explorations of hot spots in cancer therapy, such as tumor immunotherapy and ferroptosis, in various HNSCC‐related studies and treatments." (PMID 37990988, 2023).
tumor (3 papers, 2023 to 2026). "In conclusion, this study reveals the GIPC1/TRIM21/TTC7B/mTOR/NF-κB tumor-suppressive axis in CRC and highlights the potential of GIPC1 for early diagnosis and overcoming chemoresistance in CRC patients." (PMID 41522336, 2026). "Elevated expression of tetratricopeptide Repeat Domain 7B (TTC7B) is associated with increased macrophage infiltration, disruption of the TME, and poorer patient prognosis, suggesting its role in tumor progression." (PMID 40486875, 2025). "We conducted CIBERSORT analysis using the TCGA‐HNSCC and GSE184616 datasets to examine the correlation between TTC7B expression and tumor immune cell infiltration in HNSCC." (PMID 37990988, 2023). "The results revealed a significant correlation between the expression level of TTC7B and tumor immune cell infiltration, indicating a potential involvement of TTC7B in modulating the immune microenvironment in HNSCC." (PMID 37990988, 2023). "Research on TTC7B's function in tumor progression is limited." (PMID 41522336, 2026). "Furthermore, in the shGIPC1+5-FU treatment group, TTC7B overexpression further suppressed tumor progression in DLD1 cells." (PMID 41522336, 2026). "Furthermore, our study unveiled a close relationship between TTC7B expression and the extent of immune cell infiltration, potentially contributing to tumor migration and invasion by facilitating macrophage infiltration." (PMID 37990988, 2023). "Histological analysis revealed increased protein levels of GIPC1 and TTC7B in tumors treated with GIPC1-LNPs, while the Ki67 proliferation index was significantly elevated in the control group, especially the combination therapy of GIPC1-LNPs and 5-FU notably inhibited tumor proliferation." (PMID 41522336, 2026).
TTC7B also shares sentences with these, for which no sentence is quoted: breast invasive carcinoma (1 paper); cervical squamous cell carcinoma (1); diabetes (1); endocervical adenocarcinoma (1); glioblastoma multiforme (1); infection (1); ischemic stroke (1); lung adenocarcinoma (1); lung squamous cell carcinoma (1); pancreatic adenocarcinoma (1); paraganglioma (1); pheochromocytoma (1); prostate adenocarcinoma (1); rectum adenocarcinoma (1); uterine corpus endometrial carcinoma (1).